PHGDH (phosphoglycerate dehydrogenase)
Diseases named in the same sentence as PHGDH in open-access papers (continued):
Sharing a sentence is not in itself a finding about the gene and the disease.
triple-negative breast carcinoma (20 papers, 2014 to 2025). An invasive breast carcinoma which is negative for expression of estrogen receptor (ER), progesterone receptor (PR), and human epidermal growth factor receptor 2 (HER2). "Through a similar mechanism, PHGDH causes triple-negative breast cancer cells to become resistant to doxorubicin treatment." (PMID 38577610, 2024). "It has been found that phosphoglycerate dehydrogenase (PHGDH), the rate-limiting step of serine synthesis, is overexpressed in triple-negative breast cancer, while the knockdown of PHGDH significantly affects cell growth." (PMID 35008393, 2022). "In comparison, PHGDH overexpression has been reported mainly in ER-negative, especially, triple-negative breast cancer cells." (PMID 34436421, 2021). "There was a previous study suggesting that PHGDH can also produce 2-HG in triple-negative breast cancer cells." (PMID 34436421, 2021). "The serine biosynthesis pathway recently became of interest to the cancer research community, as a subset of triple negative breast cancers harbor an amplification of PHGDH leading to a corresponding overexpression of this serine biosynthesis enzyme." (PMID 31186416, 2019). "Moreover, in triple negative breast cancer, PHGDH supports Ser synthesis functional to produce glutathione, which plays a protective role against doxorubicin-induced oxidative stress." (PMID 40640948, 2025). "In triple-negative breast cancer (TNBC) cells exposed to doxorubicin, the glucose flux for serine synthesis was increased by upregulating PHGDH." (PMID 32226297, 2020). "PHGDH was also shown to generate an oncometabolite 2-hydroxyglutarate (2-HG) in PHGDH-amplified triple-negative breast cancer cells, suggesting that this non-canonical activity of the enzyme may contribute to its tumorigenic role." (PMID 34436421, 2021).
pancreatic cancer (19 papers, 2019 to 2026). "These consistent findings emphasize that PHGDH can be utilized as a diagnostic marker and is highly important as a marker for the early detection of pancreatic cancer." (PMID 38945960, 2024). "For instance, DNA hypomethylation enables PHGDH induction in nutrient-starved pancreatic tumors, while ATF4 integrates endoplasmic reticulum stress, hypoxia, and oncogenic signals to co-activate SSP genes including PHGDH." (PMID 41486146, 2026). "In pancreatic cancer, PHGDH expression is significantly upregulated and correlates strongly with tumor size, lymph node metastasis, and clinical stage; furthermore, it serves as an independent prognostic biomarker in affected patients." (PMID 41415540, 2025). "Increased expression of PHGDH is associated with tumour size, lymph node metastasis, and TNM stage of patients with pancreatic cancer." (PMID 37664062, 2023). "In pancreatic cancer, PHGDH enhances mRNA translation by interacting with eIF4A1 and eIF4E, thereby promoting cancer development." (PMID 36578934, 2022). "Although the involvement of G9a-HP1γ interaction in PHGDH expression needs to be directly evaluated, it has been recently demonstrated that HP1γ can promote aerobic glycolysis in pancreatic cancer cells." (PMID 35619118, 2022). "Iox A was identified as a novel natural PHGDH inhibitor with high specificity and low toxicity for the treatment of pancreatic cancer." (PMID 32226297, 2020). "The systematic studies from the cellular level to the animal experiments and further to the clinical patients analysis convincingly demonstrate the importance of PHGDH in pancreatic cancer development." (PMID 30744688, 2019). "A systematic investigation proved that PHGDH expression was critical for pancreatic cancer development." (PMID 30744688, 2019). "Knockdown and overexpression were performed to investigate the roles of PHGDH on pancreatic cancer cell proliferation, colony formation and tumor growth." (PMID 30744688, 2019). "According to our latest data, PHGDH expression regulates the cross talk and chemokine expression in pancreatic cancer cells and fibroblast in the tumor microenvironment, which facilitates cancer cells invasion and distribution to distant organs." (PMID 30744688, 2019). "The combination of PHGDH inhibitor and chemotherapeutics provides a prospective therapeutic strategy to treat advanced pancreatic cancer." (PMID 30744688, 2019). "The mechanisms of PHGDH promoting pancreatic cancer development were studied by identifying the interacting proteins and detecting the regulatory functions on translation initiations." (PMID 30744688, 2019). "Moreover, PHGDH facilitates pancreatic cancer progression in vivo by enhancing translation initiation through interactions with eIF4A1 and eIF4E, whereas its downregulation significantly suppresses tumor growth and prolongs overall survival." (PMID 41415540, 2025). "Mechanistically, PHGDH interacted with the translation initiation factors eIF4A1 and eIF4E and facilitated the assembly of the translation initiation complex eIF4F to promote the development of pancreatic cancer." (PMID 30744688, 2019). "Besides catalyzing serine synthesis, PHGDH promotes pancreatic cancer development through enhancing the translation initiations by interacting with eIF4A1 and eIF4E." (PMID 30744688, 2019). "Inhibiting PHGDH expression and disrupting the interactions between PHGDH and eIF4A1/eIF4E provide new prospects for anti-tumor therapeutics designs, which are meaningful for improving the pancreatic cancer treatment effect and prolonging the overall survival of clinical patients." (PMID 30744688, 2019). "Therefore, PHGDH could serve as an important prognostic indicator and therapeutic target for pancreatic cancer." (PMID 37664062, 2023). "However, the defined functions of PHGDH in pancreatic cancer are barely understood." (PMID 30744688, 2019).
pancreatic cancer (continued). "The expression of PHGDH in pancreatic cancer patients is related to tumor size, lymph node metastasis, and TNM stage of pancreatic cancer patients; in addition, it is an independent prognostic indicator." (PMID 37147729, 2023). "In the human pancreatic cancer cell lines BxPC-3 and SW1990, knockdown of PHGDH inhibits the cell proliferation, migration, and invasion abilities by downregulating the expression of cyclin B1, cyclin D1, MMP-2, and MMP-9." (PMID 32226297, 2020). "Similarly, in human pancreatic cancer tissues, the proportion of cells with positive PHGDH expression was greater than that in adjacent nontumor tissues." (PMID 38945960, 2024). "Decreased serine biosynthesis pathway by knocking out the PHGDH gene decreased pyruvate production (i.e., reduced levels of 13C-glucose labelled pyruvate), which is highly expressed in PDAC cells, suggesting a protective effect of serine against pancreatic cancer development." (PMID 35565328, 2022). "To investigate the non-enzymatic function of PHGDH, we explored whether PHGDH interacted with some proteins to regulate pancreatic cancer cells behavior." (PMID 30744688, 2019).
colon carcinoma (16 papers, 1988 to 2026). "Colon cancer patients with higher PHGDH expression were associated with shorter overall survival and recurrence-free survival (P<0.05)." (PMID 39670663, 2025). "Phosphoglycerate dehydrogenase (PHGDH), the rate-limiting enzyme of the endogenous serine synthesis pathway, is highly expressed in colon cancer and significantly correlates with shorter OS in patients, serving as an independent adverse prognostic indicator." (PMID 41614944, 2026). "We previously performed metabolomics and transcriptomic analyses of two-dimensional cultured colon cancer cells after targeted inhibition of PHGDH." (PMID 39670663, 2025). "To clarify the effect of targeted inhibition of PHGDH on the expression of colon cancer organoids, we performed a transcriptomic analysis of NCT-503 treated CRC11." (PMID 39670663, 2025). "In our study, the role of PHGDH in serine metabolism in colon cancer organoids was clarified by multi-omics analysis to provide new knowledge for an in-depth understanding of serine metabolism and PHGDH function in colon cancer." (PMID 39670663, 2025). "This suggested that NCT-503 can indeed inhibit the proliferation of PHGDH-dependent colon cancer organoids." (PMID 39670663, 2025). "Previously, we used multi-omics techniques to investigate the role of PHGDH in the serine metabolism of two-dimensional cultured colon cancer cells." (PMID 39670663, 2025). "The results showed that inhibition of PHGDH significantly inhibited the proliferation of colon cancer organoids." (PMID 39670663, 2025). "Immunohistochemical tests showed that the expression of PHGDH in colon cancer organoids numbered CRC11 and its parental tissues was strongly positive, while the expression of PHGDH in colon cancer organoids numbered CRC3 and its tissue of origin was negative." (PMID 39670663, 2025). "As a rate-limiting enzyme in the endogenous serine de novo synthesis pathway, 3-Phosphoglycerate dehydrogenase (PHGDH) has been widely concerned about its role in a variety of tumors including colon cancer and the development of inhibitors." (PMID 39670663, 2025). "Meanwhile, ATF4 activates PHGDH transcription to subsequently increase its protein levels in colon cancer cells under serine deprivation." (PMID 40598535, 2025). "Our study confirms for the first time that the selective PHGDH inhibitor NCT-503 has a significant proliferative inhibitory effect on colon cancer organoids." (PMID 39670663, 2025). "In the present study, we analyzed the transcriptomic and metabolomic changes in colon cancer organoids by targeting inhibition of PHGDH." (PMID 39670663, 2025). "In order to better understand the response of colon cancer to PHGDH inhibition, we used colon cancer PDOs to analyze the metabolomics and transcriptomic changes after PHGDH inhibition." (PMID 39670663, 2025). "Serine metabolism has been reported to contribute to CRC metabolism and growth and enzymes involved in serine synthesis such as phosphoglycerate dehydrogenase (PHGDH) are found in higher levels in colonic tumor tissue than paired normal tissue." (PMID 35208238, 2022). "Clinically, YAP was significantly activated in colon tumor tissues and positively correlated with the expression of phosphoglycerate dehydrogenase (PHGDH) and USP7." (PMID 34055773, 2021). "A positive correlation between the expression of the deubiquitinating enzyme USP7, the YAP target gene CTGF, and the serine metabolic enzyme PHGDH was detected in colon cancer tissues." (PMID 34055773, 2021). "All in all, in this study, we selected colon cancer organoids with high PHGDH expression, analyzed the transcriptomic and metabolomic changes through targeted inhibition of PHGDH, and found that inhibition of PHGDH significantly inhibited the proliferation of colon cancer organoids." (PMID 39670663, 2025). "Therefore, in this study, patient-derived colon cancer organoids were treated with PHGDH-specific inhibitors to further understand the function of PHGDH." (PMID 39670663, 2025).
colon carcinoma (continued). "Therefore, in our study, a colon cancer organoid with high PHGDH expression was selected and analyzed for transcriptomic and metabolomic changes through targeted inhibition of PHGDH." (PMID 39670663, 2025). "Treatment with CBR5884, a PHGDH-specific inhibitor, restricts colon cancer cell proliferation." (PMID 40598535, 2025). "Therefore, targeted inhibition of PHGDH to inhibit serine metabolism is expected to become a new strategy for the treatment of colon cancer." (PMID 39670663, 2025). "We applied NCT-503 to CRC11 to observe the effect of inhibiting PHGDH in colon cancer." (PMID 39670663, 2025). "The transcriptome, metabolome, and combined omics analysis showed that the changes in colon cancer organoids after inhibition of PHGDH were mainly involved in PRSS1 and PRSS56, steroid hormone biosynthesis, phenylalanine metabolism, ascorbate and aldarate metabolism, and tyrosine metabolism." (PMID 39670663, 2025). "In our previous study, we studied PHGDH in colon cancer cell lines." (PMID 39670663, 2025). "Patients with lung and colon cancers with high PHGDH expression have poor prognoses." (PMID 36319669, 2022). "It has been shown that the expression of PHGDH is regulated by many transcription factors, such as HOXA10, SMAD3 and ATF3, in endometrial endothelial cells, pulmonary epithelial cells and colon cancer cells." (PMID 39962071, 2025). "To further explore the relationship between PHGDH, USP7, and CTGF, we evaluated the mRNA expression of PHGDH, USP7, and CTGF in tissues from 87 patients with colon cancer via qRT-PCR." (PMID 34055773, 2021). "In future studies, we can screen drug-resistant organoid strains in our laboratory’s colon cancer organoid bank, and try to combine NCT-503 or CBR-5884 with various chemotherapy regimens to explore new strategies of PHGDH inhibitors in the treatment of colon cancer." (PMID 39670663, 2025). "Studies have reported that PHGDH protein is highly expressed in colon cancer and has a significant negative correlation with the prognosis of colon cancer." (PMID 39670663, 2025). "PHGDH, PSAT1, and PSPH were reported to be overexpressed in colon cancer." (PMID 34055773, 2021). "Moreover, PHGDH was positively correlated with the TNM stage as well as the tumor size and was an independent predictor of poor prognosis in patients with colon cancer." (PMID 34055773, 2021). "However, studies on serine metabolic reprogramming and PHGDH function based on the organoid technology platform of colon cancer have not yet been carried out." (PMID 39670663, 2025). "Moreover, PHGDH monoubiquitinated by CUL4A, resulting in an increase in SAM expression to upregulate the expression of cell adhesion genes (laminin subunit γ2 and cysteine-rich angiogenic inducer-61), further promoting the metastasis of colon cancer." (PMID 37187454, 2023). "Moreover, in colon cancer tissues from patients, YAP was positively related by PHGDH and USP7." (PMID 34055773, 2021).
liver cancer (14 papers, 2021 to 2025). An epithelial or non-epithelial malignant neoplasm that arises from the liver. "Interestingly, PHGDH also promotes the translation of mitochondrial DNA-encoded proteins and sustains respiration in liver cancer cells." (PMID 40640948, 2025). "To test whether loss of nuclear PHGDH or ACT domain deletion affects liver cancer cells, we first validated cancer cell proliferation using PHGDH KD cells rescued with PHGDH‐NES or PHGDH‐dACT." (PMID 37078828, 2023). "In liver cancer cells, nuclear PHGDH interacts with nuclear c-Myc to form a complex, which drives the expression of CXCL1 and IL-8 via the PHGDH/p300/c-Myc/AF9 transactivation axis." (PMID 39905317, 2025). "PHGDH can localize to the inner mitochondrial membrane in liver cancer cells and promote mitochondrial translation and respiration to enhance the recycling efficiency of the mitochondrial ribosome." (PMID 40383841, 2025). "In liver cancer, nuclear PHGDH forms a complex with c-Myc, which drives chemokine CXCL1 and IL8 expression, required to recruit neutrophils and tumor associated macrophages to the liver, sustaining tumor progression." (PMID 40640948, 2025). "Phosphoglycerate dehydrogenase (PHGDH) methylation has been linked to serine production and the development of liver cancer, according to a recent study." (PMID 39528487, 2024). "Despite being downregulated at the mRNA and protein levels, PRMT1-mediated R236 methylation activates PHGDH, promoting serine production, redox homeostasis, and the development of liver cancer." (PMID 39528487, 2024). "Consistent with our results, PHGDH translocate to mitochondria and stimulate mitochondrial translation and tumor progression in liver cancer." (PMID 39207107, 2024). "In line with our findings, in liver cancer, PHGDH relocates to mitochondria and stimulates mitochondrial translation and tumor progression." (PMID 39207107, 2024). "To validate the localization of PHGDH in human liver cancer tissues, we analyzed 87 tumor samples that showed positive signals." (PMID 37078828, 2023). "We further detected the localization of PHGDH in clinical human liver cancer samples and found that 66 of 87 samples showed nuclear PHGDH signals." (PMID 37078828, 2023). "Consistent with the evidence that PHGDH localizes to the nucleus at the cellular level, we also observed the nuclear localization of PHGDH advanced liver cancer in both human and mouse models." (PMID 37078828, 2023). "When we analyzed the expression of PHGDH and cMyc, we found their genes exhibit strong clinical synergy and can predict survival in patients with liver cancer." (PMID 37078828, 2023). "To verify the role of PHGDH/cMyc axis‐regulated Cxcl1/Il8 expression in liver cancer progression, we delivered AAV carrying Phgdh‐WT or Phgdh‐dACT under the thyroid hormone binding globulin promoter into PhgdhLKO adult mice." (PMID 37078828, 2023). "Thus, the translocation of PHGDH from the cytoplasm to the nucleus is an unfavorable biomarker in patients with liver cancer." (PMID 37078828, 2023). "To verify whether PHGDH and cMyc have synergistic effects in the clinical setting, we performed IHC with clinical liver cancer samples using antibodies against PHGDH, cMyc, and cMyc‐AcK148." (PMID 37078828, 2023). "Indeed, a very early study reported that PHGDH activity was enhanced in tumors from a rat liver cancer model." (PMID 36823188, 2023). "Therefore, the liver cancer cells with nuclear PHGDH demonstrate a new function for metabolic enzymes in regulating the reciprocal action of tumor cells and the microenvironment independent of metabolic enzyme activity." (PMID 37078828, 2023). "The nuclear intensity of PHGDH could mark the progression of liver cancer, and the PHGDH/cMyc axis represents a new layer of metabolic enzyme regulation of the reciprocal action of tumor cells and the microenvironment independent of PHGDH activity." (PMID 37078828, 2023).
liver cancer (continued). "However, this and a prior study confirmed that PHGDH contributes to liver cancer progression." (PMID 37078828, 2023). "Extracted nuclei from two human liver cancer cell lines (PLC/PRF/5, Hep3B) showed partial localization of PHGDH." (PMID 37078828, 2023). "In liver cancer cells, the aspartate kinase‐chorismate mutase‐tyrA prephenate dehydrogenase (ACT) domain of PHGDH binds nuclear cMyc to form a transactivation axis, PHGDH/p300/cMyc/AF9, which drives chemokine CXCL1 and IL8 gene expression." (PMID 37078828, 2023). "Consistent with our recent findings in pediatric liver cancer, we also observed that CM272 markedly reduced the expression of amino acid metabolic enzymes (ASNS, PYCR1, BCAT2), as well as genes involved in the serine pathway (PHGDH, PSPH, PSAT1)." (PMID 39810240, 2025). "Similarly, LINC01564 is upregulated by ATF4 and activates phosphoglycerate dehydrogenase (PHGDH), facilitating serine biosynthesis and metabolic reprogramming in liver cancer cells." (PMID 40777108, 2025). "Herein, we discovered a distinct function of PHGDH, which promotes cMyc transactivation via the ACT domain to drive promoter expression of genes required for neutrophil recruitment and TAM enrichment in liver cancer tissue, driving liver cancer advancement." (PMID 37078828, 2023). "Consistent with the results obtained in the induced mouse liver cancer model, PHGDH and cMyc interacted in human liver cancer cell lines independent of PHGDH enzyme activity." (PMID 37078828, 2023). "Studies have demonstrated that in liver cancer cells, the aspartate kinase-chorismate mutase-tyrosine aminotransferase (ACT) domain of PHGDH binds to nuclear cMyc, forming a transactivation axis involving PHGDH, p300, cMyc, and AF9, which drives the gene expression of chemokines CXCL1 and IL8." (PMID 40342932, 2025).